ANKRD11 (ankyrin repeat domain 11)
Diseases named in the same sentence as ANKRD11 in open-access papers (continued):
Sharing a sentence is not in itself a finding about the gene and the disease.
KBG syndrome (continued). "The FBN2 variant causes Beals syndrome (Congenital contractual arachnodactyly) (MIM:121050), which is characterized by arachnodactyly and camptodactyly; The ANKRD11 mutation causes KBG syndrome, which may contribute to the ASD in this patient." (PMID 35346302, 2022). "On the other hand, heterozygous deletions or splice site mutations in the ANKRD11 gene have been found in patients with KBG syndrome, characterized by macrodontia, distinctive craniofacial and skeletal anomalies, short stature, and neurological problems including ID." (PMID 36551904, 2022). "In one study, clinical features are hypothesized to result from the combined effect of mutations in KDM1A and ANKRD11 (Ankrin Repeating Domain-Containing protein 11), the latter of which is associated with KBG syndrome involving craniofacial phenotypes." (PMID 33954026, 2021). "It has been speculated that haploinsufficiency of ANKRD11 may lead to increased cancer risk in patients with KBG syndrome." (PMID 34604130, 2021). "KBG syndrome (MIM 148050) due to heterozygous ANKRD11 variants manifests variably as macrodontia, intellectual disability and skeletal/craniofacial defects, including conductive or mixed hearing loss–these features do not fit the patient’s clinical presentation." (PMID 33924653, 2021). "Mutations or deletions of ANKRD11 gene are responsible for the symptoms of KBG syndrome." (PMID 34604130, 2021). "Herein, we describe a detailed clinical presentation of KBG syndrome in 23 patients: 13 with a pathogenic single nucleotide variant (SNV) in the ANKRD11 gene and 10 with a 16q24 rearrangement encompassing the ANKRD11 gene (nine patients with a microdeletion and one with a microduplication)." (PMID 34440431, 2021). "Such alterations have been reported for almost all individuals with KBG syndrome independently of the underlying molecular defect, namely ANKRD11 variant or deletion, although for two patients with an ANKRD11 deletion no permanent teeth anomalies were reported." (PMID 28422132, 2017). "KBG syndrome is a neurodevelopmental disorder (NDD) caused by loss-of-function of the ANKRD11 gene." (PMID 29311865, 2017). "Patients with KBG syndrome because of a LoF variants in ANKRD11 gene may show: mild-to-moderate intellectual disability, epilepsy or EEG anomalies, brain malformations, behavioral and autistic spectrum disorders." (PMID 28422132, 2017). "Only four missense ANKRD11 variants have been reported to cause KBG syndrome." (PMID 29258554, 2017). "Individuals with KBG syndrome have been found to have heterozygous mutations leading to haploinsufficiency of the ankyrin repeat domain 11 (ANKRD11) gene or a 16q24 microdeletion that encompasses ANKRD11." (PMID 27900361, 2016). "Within our cohort, we identified 20 different ANKRD11 mutations in 32 patients with KBG syndrome." (PMID 27667800, 2016). "The ANKRD11 gene encodes an ankryin repeat domain-containing protein which inhibits ligand-dependent activation of transcription with mutations causing the KBG syndrome characterized by craniofacial features, short stature, skeletal anomalies, seizures and intellectual disability." (PMID 25574603, 2015). "KBG syndrome (KBGS) is a neurodevelopmental disorder caused by the Ankyrin Repeat Domain 11 (ANKRD11) haploinsufficiency." (PMID 35682590, 2022). "It is possible that, in KBG syndrome, in which delayed closure of a wide fontanel is a common feature, craniosynostosis could result from disturbances of cranial suture development associated with the ANKRD11 gene." (PMID 34440431, 2021). "The KBG syndrome (KBGS) affects several systems caused by the mutation of the ANKRD11 gene." (PMID 40574944, 2025). "The newborn was diagnosed with KBG syndrome based on the revised diagnostic criteria of KBGS established in 2016, in conjunction with the pathogenic variant of the ANKRD11 gene." (PMID 41230445, 2025). "In summary, we report three individuals presenting with KBG syndrome due to the deletion of non-coding exon 1 of ANKRD11." (PMID 40004465, 2025).
KBG syndrome (continued). "Our findings underscore the importance of the genomic evaluation of non-coding regions of ANKRD11 in individuals with suspected KBG syndrome and suggest the utility of transcriptome analysis in establishing a molecular diagnosis of KBG syndrome." (PMID 40004465, 2025). "The majority of ANKRD11 mutations associated with KBG syndrome are nonsense, frameshift and splicing mutations, in addition to chromosomal deletions involving the full or partial sequence of the gene, all of which could result in a reduction in the ANKRD11 transcript level." (PMID 40004465, 2025). "Our molecular analysis showed that this deletion leads to reduction in the ANKRD11 transcript and global transcriptome alterations similar to those seen in KBG syndrome patients." (PMID 40004465, 2025). "Our findings support the inclusion of ANKRD11 in the differential for pediatric dystonia and suggest a potential, previously underrecognized neurologic feature of KBG syndrome." (PMID 40760574, 2025). "From a clinical perspective, this is the first case of a clear link between ANKRD11, KBG syndrome, and OB deficits." (PMID 38616269, 2024). "WES detected a pathogenic de novo deletion c.2404_2407del (p.Leu802LysfsTer60) in exon 9 of ANKRD11, leading to a diagnosis of KBG syndrome." (PMID 38334877, 2024). "ANKRD11 haploinsufficiency was later identified in KBG syndrome (KBGS) patient-focused clinical and molecular studies, confirming the dominant pathogenic mechanism responsible for this condition (OMIM#148050)." (PMID 39135054, 2024). "Taken together, our results demonstrate a novel and critical role for ANKRD11 in OB development and suggest OB size or olfaction evaluations should be considered upon KBG syndrome diagnosis for appropriate genetic counseling and to improve clinical care." (PMID 38616269, 2024). "To date, a total of 1181 gene mutations of ANKRD11 have been cataloged in the NCBI (National Center for Biotechnology Information) database, with 590 attributed to KBG syndrome." (PMID 39831200, 2024). "Genetic variants in Ankyrin Repeat Domain 11 (ANKRD11) and deletions in 16q24.3 are known to cause KBG syndrome, a rare syndrome associated with craniofacial, intellectual, and neurobehavioral anomalies." (PMID 35970914, 2022). "The fact that wide, delayed closing fontanels were observed in more than a half of our patients with KBG syndrome confirms the role of the product of ANKRD11 gene in skull formation and suture fusion." (PMID 34440431, 2021). "Ultimately, early diagnosis and better understanding of ANKRD11 function will assist with genetic counseling for patients with KBG syndrome and their affected families." (PMID 33996804, 2021). "Nine of 13 (69%) patients tested with next-generation sequencing technology were previously suspected to have KBG syndrome; thus, the ANKRD11 gene was analyzed by the first choice among the genes available for testing in the gene panel." (PMID 34440431, 2021). "The fact that wide, delayed closing fontanels were observed in more than half of our patients with KBG syndrome confirms the role of the ANKRD11 gene in skull formation and suture fusion." (PMID 34440431, 2021). "Duplication involving ANKRD11 was found in patients with KBG syndrome, which exhibits severe developmental delay and intellectual disability." (PMID 34947998, 2021). "The results of this study expand the spectrum of ANKRD11 variants in KBG patients and provide clinical phenotypic data for KBG syndrome at an early age." (PMID 33653342, 2021). "Further studies will help delineating the spectrum of phenotype, details of ANKRD11 function and dysfunction in KBG syndrome, and missing variants either in ANKRD11 or in additional genes in patients with a clinical diagnosis of KBG syndrome." (PMID 29258554, 2017). "This is analogous to many other rare neurogenetic syndromes: for instance, KBG syndrome (caused by ANKRD11 mutations) also shows a high rate of EEG anomalies without a distinct syndrome-specific pattern." (PMID 40968989, 2025).
KBG syndrome (continued). "Short-read whole-genome sequencing combined with advanced bioinformatics analyses were successful in uncovering a de novo pericentric 87-Mb inversion with breakpoints in TSC2 and ANKRD11, which explains the TSC clinical diagnosis, and confirms a second underlying monogenic disorder, KBG syndrome." (PMID 38253421, 2024). "Furthermore, we found a double disease-causing heterozygous variant of FBN2 and ANKRD11 in a patient with blended phenotypes consisting of CCA and KBG syndrome." (PMID 35360850, 2022). "A search for novel pathogenic variants in three patients with suspected KBG syndrome who did not harbor ANKRD11 mutations resulted in the identification of an exon 1–17 deletion and frameshift mutations in SETD5." (PMID 36685966, 2022). "KBG syndrome (KBGS) is a rare autosomal dominant inherited disease that involves multiple systems and is associated with variations in the ankyrin repeat domain 11 (ANKRD11) gene." (PMID 35330407, 2022). "More recently, a girl with KBG syndrome features but without an ANKRD11 mutation was found to harbor a non-sense mutation in SETD5." (PMID 36685966, 2022). "Similarly, studies in other organ systems often involved in KBG syndrome will further clarify the role of Ankrd11 in epigenetic and genomic control of tissue and organ development." (PMID 33996804, 2021). "Three patients without ANKRD11 mutation, suspected earlier to have KBG syndrome, were diagnosed with different rare genetic syndromes." (PMID 34440431, 2021). "Thus, the homozygous deletion of Ankrd11 in a tissue-specific manner provides a powerful approach to model the KBG syndrome phenotypes in mice." (PMID 33996804, 2021). "Also shRNA mediated knockdown of Ankrd11 (ANKRD11 [MIM: 611192]), of which haploinsufficiency in humans is associated with neurodevelopmental KBG syndrome (MIM: #148050), resulted in an increased number of shortened neurites in a mouse model." (PMID 33149206, 2020). "KBG syndrome, caused by ANKRD11 gene haploinsufficiency, is a chromatin related syndrome not formally belonging to this category." (PMID 32793091, 2020). "The loss of ANKRD11 gene confirms the diagnosis of KBG syndrome but does not elucidate the pediatric phenotype providing a counseling challenge." (PMID 29375862, 2017). "The median facial gestalt scores for the individuals with mutations in non-NIPBL cohesin-component genes are very similar to those in individuals with ANKRD11 mutations which have been associated with the ‘non-cohesinopathy’, KBG syndrome." (PMID 25125236, 2014). "However, recent studies have identified SETD5 mutations in some KBG syndrome patients without ANKRD11 mutations." (PMID 36685966, 2022). "Here, we report that mice with heterozygous deletion of Ankrd11 in neural crest cells (Ankrd11nchet) display a mild midfacial hypoplasia including reduced midfacial width and a persistent open fontanelle, both of which mirror KBG syndrome patient facial phenotypes." (PMID 33996804, 2021). "Our study identifies Ankrd11 as a critical regulator of intramembranous ossification and palate development and suggests that Ankrd11nchet and Ankrd11ncko mice may serve as novel pre-clinical models for KBG syndrome." (PMID 33996804, 2021). "Our study identifies Ankrd11 as a critical regulator of intramembranous ossification and palate development and suggests that Ankrd11nchet and Ankrd11ncko mice may serve as pre-clinical models for KBG syndrome in humans." (PMID 33996804, 2021). "Absence of an ANKRD11 mutation does not exclude the diagnosis of KBG syndrome." (PMID 29258554, 2017).
KBG syndrome (continued). "Notably, both IDD23 and KBG syndrome patients frequently exhibit microcephaly, underscoring the crucial role of SETD5- and ANKRD11-mediated control of NSPC proliferation in maintaining proper brain development." (PMID 41283518, 2025). "The inversion disrupts TSC2 and ANKRD11, resulting in dual diagnosis of TSC/KBG syndromes." (PMID 38253421, 2024). "While our work has not tested the role of ANKRD11 in non-neural crest-derived heart tissues, our results suggest neural crest involvement in KBG syndrome cardiac defects." (PMID 38951500, 2024). "KBG syndrome (KBGS; OMIM #148050) is an autosomal dominant neurodevelopmental disorder (NDD) first described in 1975 that is caused by the haploinsufficiency of the ANKRD11 gene (OMIM #611192) at 16q24.3 due to heterozygous pathogenic variants or chromosomal imbalances." (PMID 35682590, 2022). "Performing a next-generation sequencing panel, including the ANKRD11 gene for cases of developmental delay with/without short stature may be helpful to identify hitherto undiagnosed KBG syndrome patients." (PMID 33262785, 2020).
Intellectual disability (18 papers, 2015 to 2025). "Research suggests that the pathogenic variants of ANKRD11 gene are a common Mendelian cause of developmental delay and that it is one of the major genes associated with intellectual disability." (PMID 34604130, 2021). "In many different genetic studies, scientists underline the role of ANKRD11 gene which, when deleted, may induce intellectual disability, brain abnormalities and neurodevelopmental disorders including ASD (Autism spectrum disorder)." (PMID 34604130, 2021). "ANKRD11 mutations have been associated with diseases with distinctive craniofacial features, short stature, skeletal anomalies, global developmental delay, seizures and intellectual disability." (PMID 33338084, 2020). "ANKRD11 variants are also associated with KBGS as well as with various other neurodevelopmental disorders such as autism spectrum disorder and intellectual disability." (PMID 41230445, 2025). "Ankyrin repeat domain 11 (Ankrd11) is down-regulated in METH-treated cortical neurons and is known to be associated with intellectual disability." (PMID 41002437, 2025). "Truncated variation in the ANKRD11 gene is more likely to lead to global growth retardation and intellectual disability/learning difficulties than missense variation in ANKRD11." (PMID 35330407, 2022). "We observed that patients with truncation variation in the ANKRD11 gene had a higher frequency of global developmental delays and intellectual disability/learning difficulties than those with missense variation." (PMID 35330407, 2022). "The frequency of global developmental delays and intellectual disability/learning difficulties in patients with truncated ANKRD11 gene variation was higher than that in patients with missense variation in the ANKRD11 gene (p < 0.05)." (PMID 35330407, 2022). "However, owing to the low number of patients, the authors could not exclude that the severity of neurological symptoms and intellectual disability was greater in cases where the deletion included other genes, besides ANKRD11." (PMID 28422132, 2017).
developmental delay (14 papers, 2015 to 2024). "Our findings suggest that mutation of ANKRD11 is a common Mendelian cause of developmental delay." (PMID 27667800, 2016).
Cornelia de Lange syndrome (9 papers, 2020 to 2025). A rare syndrome characterized by low birth weight, delayed growth, intellectual disabillity, behavioral problems, and a distinctive facial appearance (thin, arched eyebrows, low set ears, small teeth, and small nose). "Mutations of the ANKRD11 gene (which is associated with KBGS) have also been identified in individuals with Cornelia de Lange syndrome and other developmental disorders, with this phenotypic overlap increasing the challenge of clinical diagnosis." (PMID 36012925, 2022). "The most common cohesinopathy, Cornelia de Lange syndrome, is caused by dysfunction in a variety of cohesin subunits, such as NIPBL, SMC1A, SMC3, RAD21, BRD4, HDAC8, and ANKRD11." (PMID 40943870, 2025). "Variants in genes encoding various structural or functional components of the cohesin complex, including RAD21, SMC1A, SMC3, BRD4, STAG1/2, NIPBL, HDAC8, WAPL, ANKRD11 and in single individuals PDS5A and ESPL1, have been implicated in Cornelia de Lange Syndrome (CdLS)." (PMID 32193685, 2020). "Cornelia de Lange syndrome (CdLS) has seven disease-associated genes; two of them localize (SMC1A and SMC3) to cilia and two of them (ANKRD11 and HDAC8) are implicated in cilia." (PMID 37542408, 2023).
autism (8 papers, 2015 to 2024). Persistent deficits in social interaction and communication and interaction as well as a markedly restricted repertoire of activity and interest as well as repetitive patterns of behavior. "While ANKRD11 variants have been linked to autistm spectrum disorder, none of the interviewed children appeared to have a severe form of autism as they were interactive, social, and maintained eye contact." (PMID 35970914, 2022). "Examples of these genes include CHD7, ANKRD11, and SON which are robustly associated with both autism and severe developmental disorders." (PMID 36702863, 2023).